TLR8 (toll like receptor 8)
Diseases named in the same sentence as TLR8 in open-access papers (continued):
Sharing a sentence is not in itself a finding about the gene and the disease.
macrophage activation syndrome (1 paper, 2024). A complication of rheumatic disease that is caused by excessive activation and uncontrolled proliferation of T lymphocytes and well-differentiated macrophages. "A study recently showed that macrophage-activation syndrome associated with missense mutations is due not only to TLR7 but also to TLR8; this is important particularly in males since TLR8 is also located on the X chromosome." (PMID 39062904, 2024).
malignant brain tumors (1 paper, 2021). "Eight PRRs were identified as up-regulated after the second immune challenge, including perlucin 4, C1q domain containing protein 2, scavenger receptor class B-like protein, deleted in malignant brain tumors 1 protein-like, TLR, TLR2, TLR3 and TLR8." (PMID 34295333, 2021).
mantle cell lymphoma (1 paper, 2014). Mantle cell lymphoma is a rare form of malignant non-Hodgkin lymphoma affecting B lymphocytes in the lymph nodes in a region called the ``mantle zone''. "In mantle cell lymphoma (MCL), TLR1, TLR4, TLR7, TLR9 and TLR10 exhibit significant mRNA levels, whereas TLR2, TLR3, TLR5 and TLR8 are negative." (PMID 25112836, 2014).
meningoencephalitis (1 paper, 2015). Inflammation of the meninges and brain, generally secondary to an infectious cause. "The meningoencephalitis symptom phenotype cluster among seropositive patients was associated with polymorphisms in DDX58/RIG-I and TLR8." (PMID 25756647, 2015).
Miscarriage (1 paper, 2024). A pregnancy that ends at a stage in which the fetus is incapable of surviving on its own, defined as the spontaneous loss of a fetus before the 22th week of pregnancy. "Additionally, the impact of herpes simplex viruses 1 and 2 on the expression of TLR2, TLR3, TLR4 and TLR8 in predicting miscarriage onset has been studied." (PMID 39273663, 2024).
morbid obesity (1 paper, 2016). An excess of body weight, normally defined as an individual with a body mass index greater than 35 or a body weight greater than one hundred percent of ideal body weight. "Therefore, TLR8 expression changes need to be further investigated with regard to putative agonists like cellular RNAs and alarmins (e.g. HMGB1) which are known to be released during lipolysis in morbid obesity." (PMID 27980459, 2016).
mycobacterial infection (1 paper, 2022). "In a pathway analysis in a zebrafish larval mycobacterial infection model, the expression of the Tlr8 pathway connected to vitamin D signaling was strongly affected in a tlr2 mutant, which implicates a link between Tlr2 and Tlr8 signaling." (PMID 35205112, 2022).
myeloid malignancies (1 paper, 2025). "This suggests that TLR8 expression could potentially serve as a predictive biomarker of response to TLR7/8 agonists in myeloid malignancies." (PMID 40858756, 2025).
myocardial infarction (1 paper, 2018). Gross necrosis of the myocardium, as a result of interruption of the blood supply to the area, as in coronary thrombosis. "In this study, we observed highly increased gene expression levels of Tlr1, Tlr2, Tlr6, Tlr7, Tlr8, Tlr9 as well as Irf7 in the scar tissue after myocardial infarction, indicating their relevance to a proper cardiac wound healing." (PMID 29538462, 2018). "After myocardial infarction, gene expression levels of the intracellular localized Tlr7, Tlr8, and Tlr9 were significantly increased when compared to their healthy controls." (PMID 29538462, 2018).
myocarditis (1 paper, 2018). Myocarditis is a condition that is characterized by inflammation of the heart muscle (myocardium). "Interestingly, merely the intracellular localized TLRs Tlr3, Tlr8, and Tlr9 demonstrated elevated gene expression also at the chronic stage of myocarditis (28 days pi CVB3)." (PMID 29538462, 2018).
osteosarcoma (1 paper, 2021). A usually aggressive malignant bone-forming mesenchymal neoplasm, predominantly affecting adolescents and young adults. "Our results showed that compared with osteoblasts, CPEB3, EIF4E3, RBM34, RPS27L, RPS29 and TDRD6 were down-regulated in U2OS and 143B, while NXT2, TERT, TLR8 and ZC3HAV1 were up-regulated in osteosarcoma cells." (PMID 34926575, 2021).
parasite infections (1 paper, 2024). "This hypothesis is corroborated by former observations that correlate higher expression of some X-linked genes (Tlr7, Cxcr3, and Tlr8) in females compared to males with better protection against viral or parasite infections in both humans and mice." (PMID 38701219, 2024).
plaque psoriasis (1 paper, 2019). "IMO-8400 inhibits TLR7/TLR8/TLR9 under phase-II clinical trials in patients with moderate to severe plaque psoriasis." (PMID 31582899, 2019).
pneumococcal meningitis (1 paper, 2024). An acute purulent infection of the meninges and subarachnoid space caused by Streptococcus pneumoniae, most prevalent in children and adults over the age of 60. "Consequently, combining antimicrobial therapy with TLR2- and endosomal TLR–specific antagonists effectively protected mice from pneumococcal meningitis pathology and significantly inhibited S. pneumoniae–induced activation of murine macrophages and human PBMCs in which TLR8 substitutes for TLR13." (PMID 38358825, 2024). "Our study indicates the importance of murine TLR13 and human TLR8, besides TLR2, in pneumococcal meningitis pathology, and suggests their blockade as a promising antibiotic therapy adjunct." (PMID 38358825, 2024).
pneumonitis (1 paper, 2012). An inflammatory process affecting the lung parenchyma. "We initially tested the effect of RTD-1 on ssRNA (TLR8 agonist) induced responses of PBLs to compare human cell responses with those obtained in mouse SARS-CoV (a single stranded RNA virus) pneumonitis." (PMID 23236475, 2012).
polyp (1 paper, 2014). A usually exophytic mass attached to the underlying tissue by a broad base or a thin stalk. "TLR8 is also absent in T21 normal VFF and only a faint expression noted in T59, scar, and polyp VFF." (PMID 25606025, 2014).
post-traumatic stress disorder (1 paper, 2025). An anxiety disorder precipitated by an experience of intense fear or horror while exposed to a traumatic (especially life-threatening) event. "In the context of post-traumatic stress disorder (PTSD), a recent study reported altered gene-specific DNA methylation patterns, particularly involving the TLR8 gene in patients with PTSD related to childhood abuse." (PMID 40558558, 2025).
preeclampsia (1 paper, 2020). Preeclampsia is a hypertensive disorder of pregnancy that is characterized by new-onset hypertension with proteinuria presenting after 20 weeks of gestation, and depending on mild or severe forms may initially present with severe headache, visual disturbances, and hyperreflexia. "In preeclampsia, placental expression of TLR3, TLR7, and TLR8 are upregulated." (PMID 32260307, 2020).
psychosis (1 paper, 2020). "The results of our study highlight the role that TLR5 and TLR8 might play in the pathophysiology of psychosis." (PMID 32854231, 2020). "We highlight the role that TLR5 and TLR8 might have in the pathophysiology of psychosis." (PMID 32854231, 2020).
pure red-cell aplasia (1 paper, 2022). A disease characterized by normocytic, normochromic anemia, low hematocrit, reticulocytopenia, and selective erythroid hypoplasia. "In addition to TLR8-GOF, LGL cells can be found in several BMF entities, including severe aplastic anemia (SAA), paroxysmal nocturnal hemoglobinuria, and pure red cell aplasia (PRCA), as well as in autoimmune diseases (ALPS, RA/FS), hematopoietic malignancies, and plasma cell disorders." (PMID 36119097, 2022).
rectum adenocarcinoma (1 paper, 2020). An adenocarcinoma arising from the rectum. "The result illustrated that the hub genes, including NRXN1, ANK2, LPHN2, APOE, TLR8, ESR1, and so on, might be critical for rectum adenocarcinoma, and m6A modification could regulate the abnormal expression of these genes." (PMID 33680913, 2020).
Rotavirus infection (1 paper, 2010). Infection with any of the rotaviruses. "Increased mRNA for TLR8 were detected in PBMC from infants with acute rotavirus infection." (PMID 20946625, 2010).
RSV bronchiolitis (1 paper, 2009). "There were only low and similar levels of expression of neutrophil TLR2 in the three groups and of TLR8 mRNA in term infants with RSV bronchiolitis and controls (p>0.05)." (PMID 19497921, 2009). "There was no detectable expression of neutrophil TLR8 mRNA in preterm infants with RSV bronchiolitis." (PMID 19497921, 2009).
SARS-CoV infection (1 paper, 2009). "The basal gene expression of TLR-8 was high in CB DCs and the expression was nearly doubled after SARS-CoV infection at both 3 h and 9 h post infection." (PMID 19505311, 2009).
schizophrenia (1 paper, 2024). A major psychotic disorder characterized by abnormalities in the perception or expression of reality. "Higher TLR8 mRNA levels were inversely associated with cortical thickness of the cingulate gyrus, hinting at a potential link between TLR activation and structural brain changes in schizophrenia." (PMID 38792602, 2024). "Drug-naïve patients with schizophrenia exhibited increased TLR4 mRNA levels and unaltered TLR3 mRNA levels in peripheral blood mononuclear cells (PBMC), alongside elevated TLR4 and TLR8 mRNA levels and reduced TLR3 mRNA levels in white blood cells compared to healthy controls." (PMID 38792602, 2024).
skin cancer (1 paper, 2021). "Thus TLR3, TLR7/TLR8, and TLR9 activation are crucial therapeutic and adjuvant-based vaccine-oriented approaches to target skin cancers." (PMID 33510592, 2021).
skin reaction (1 paper, 2021). "Among them, TLR8 is implicated in eczematous skin reactions." (PMID 34442794, 2021).
squamous cell carcinoma (1 paper, 2024). A carcinoma arising from squamous epithelial cells. "Summarizing the Results section, significant differences were observed in the expression of various TLRs (TLR-2, TLR-3, TLR-4, TLR-7, TLR-8, and TLR-9) on selected T and B cell subpopulations between the patients with squamous cell carcinoma (SCC) and the healthy controls." (PMID 39124797, 2024).
staphylococcus aureus infection (1 paper, 2021). An infectious process in which the bacteria Staphylococcus aureus is present. "Also, during Staphylococcus aureus infections, RNase T2 cleaves single-stranded RNA (ssRNA), producing purine-2′,3′-cyclic phosphate-terminated oligonucleotides sensed by Toll-like receptor 8 (TLR8)." (PMID 34372695, 2021).
steatosis (1 paper, 2022). Increased lipid within the cytoplasm of cells. "Coincident with an alleviation of hepatic steatosis, we computationally detected the downregulation of IL-6/JAK/STAT3 signaling and the inflammatory response (e.g., Tlr8, Mlkl), together with impaired EMT (Lgals1) in the liver, while the expression of genes related to mTOR was enhanced by LY." (PMID 35737463, 2022).
temporal lobe epilepsy (1 paper, 2022). A localization-related (focal) form of epilepsy characterized by recurrent seizures that arise from foci within the temporal lobe, most commonly from its mesial aspect. "High expression of TLR8 in parvalbumin-interneurons may contribute to their high vulnerability in human temporal lobe epilepsy." (PMID 35507634, 2022).
Ureteral obstruction (1 paper, 2020). Obstruction of the flow of urine through the ureter. "In conclusion, glomerular miR-21 expression is elevated following unilateral ureteral obstruction, wherein it interacts with TLR8 in podocytes and induces production of downstream cytokines (Il1b and Il6) suggesting activation of NF-κB pathway." (PMID 33552064, 2020).
vasculitis (1 paper, 2022). "It has been shown that TLR8, a marker of macrophage M2, is significantly elevated in the acute phase of KD, suggesting that activated macrophages are a key driver of vasculitis in KD28." (PMID 36536067, 2022).
VEXAS syndrome (1 paper, 2022). An adult-onset inflammatory disease that affects only males and is caused by somatic, not germline, mutations. "Many IEIs resulting from mosaicism are also germline disorders, as in the case of most autoinflammatory disorders and ALPS, whereas few IEIs are predominantly caused by somatic mutations (eg, VEXAS syndrome, TLR8 gain-of-function, and Ras-associated autoimmune leukoproliferative disorder)." (PMID 36466883, 2022).
X-linked agammaglobulinemia (1 paper, 2012). X-linked agammaglobulinemia (XLA) is a clinically variable form of isolated agammaglobulinemia, an inherited immunodeficiency disorder (see this term), and is characterized in affected males by recurrent bacterial infections during infancy. "Impaired TLR-8-mediated IL-6 and TNF-α production in antigen-presenting cells from patients with X-linked agammaglobulinemia was observed." (PMID 22547990, 2012).
tumor (147 papers, 2012 to 2025). "The anti-cancer mechanisms reported to be associated with TLR-8-mediated activation of mDC include promoting the activation of tumor-specific CD8+ T cells, skewing CD4+ T cell responses towards Th1, and inhibiting Treg function." (PMID 36297510, 2022). "Associations were observed between TLR8 expression and smoking history, tumor site and nodal (n) status." (PMID 33452311, 2021). "Endovesicular miR-21, released by neuroblastoma cells, binds to TLR8 in surrounding tumor-associated macrophages, inducing in these cells the upregulation and the release in EVs of miR-155." (PMID 30884898, 2019). "Genes linked to both anti-viral and anti-tumor immune effector responses such as toll-like receptor 8 (TLR8), tumor necrosis factor (TNF), and interferon γ (IFN γ) were upregulated after MeVac FmIL-12 treatment." (PMID 31623390, 2019). "As a member of the Toll-like receptors (TLRs) family, TLR8 interacts with damage-associated molecular patterns (DAMPs), modulating antigen presentation and cytokine release, thereby directly influencing T-cell activation and the clearance of tumor cells." (PMID 41208992, 2025). "Treatment with R848 (an agonist of TLR7 and TLR8)-loaded β-cyclodextrin NPs (CDNP-R848) can drive M1 polarization of tumor-associated macrophages (TAMs) in the TME in multiple mouse tumor models (e.g., tumors caused by mouse colon adenocarcinoma cell line MC-38 and melanoma cell line B16-F10)." (PMID 36015256, 2022). "The relatively modest tumor growth inhibition observed in this model could be underestimated given the immune-deficient background where the TLR8’s immune modulation was largely bypassed in this model." (PMID 35006413, 2020). "The correlation between CDSE1 and TLR4, TLR7 or TLR8 expression suggests that PDAC patients with high UNR/CDSE1 expression may present a less aggressive tumor phenotype, more susceptible to be cleared by the immune response." (PMID 28763470, 2017). "In addition to evaluation of SA-β-Gal expression in tumor-treated CD4+ T cells, we investigated the effects of TLR8 signaling on the expression of other senescence-associated markers and function of tumor-induced senescent T cells." (PMID 25231413, 2014). "TLR8 stimulation may activate dendritic cells and promote the presentation of tumor-associated antigens, leading to the activation of cytotoxic T lymphocytes and anti-tumor immune responses." (PMID 38903515, 2024). "Additionally, as an innate pattern recognition receptor, Toll-like receptor 8 (TLR8) (encoded by TLR8) could enhance cytokines secretion and promote anti-tumor immunity." (PMID 33386920, 2021). "TLR7 and TLR8, as conserved innate immune molecules, play a significant role in the tumor microenvironment." (PMID 40469310, 2025). "Decreased m6A levels on 5′‐half‐tRNA fragment (5′‐half)‐GlyGCC in EVs were identified as determinants of this effect and subsequent tumour progression, acting via Toll‐like receptor 8 (TLR8)." (PMID 40326665, 2025). "Although survival analyses of TLR7 and TLR8 expression are confounded by their expression both in tumour cells and in immune cells, the strict tumour specificity of HERVH Xp22.2-AS expression reflects tumour cell-intrinsic transcriptional states." (PMID 40336011, 2025). "In AML, activation of TLR8 can lead to caspase‐3‐dependent apoptosis of tumor cells, which mediates antitumor effects." (PMID 40727252, 2025). "miR-21 also stimulates Toll-like receptors TLR7 and TLR8 in immune cells to promote tumor growth and metastasis." (PMID 39409003, 2024). "This has been demonstrated in melanoma adoptive T cell transfer therapy models, where TLR8 activation improves Treg activity and strengthens anti-tumor immune responses." (PMID 39731171, 2024). "TLR8 agonists diminish the generation of cAMP in tumor cells and restrain glycolysis in tumor-derived Tregs without interfering with the metabolism of effector T cells, thereby preventing T cell senescence." (PMID 39684260, 2024).